OBSCN-AS1 (OBSCN antisense RNA 1)
Synonyms: C1orf145; FLJ31994
Gene: Long non-coding RNA gene on chromosome 1 (228,203,503 to 228,213,664, reverse strand). Ensembl gene ENSG00000162913.
Diseases named in the same sentence as OBSCN-AS1 in open-access papers:
OBSCN-AS1 is named in the same sentence as 2 diseases in open-access papers, as found by Europe PMC text mining. Sharing a sentence is not in itself a finding about the gene and the disease.
OBSCN-AS1 shares sentences with these, for which no sentence is quoted: diabetic cardiomyopathy (1 paper); Insulin resistance (1).